STRIT1 (small transmembrane regulator of ion transport 1)
Description:
Enhances the activity of ATP2A1/SERCA1 ATPase in sarcoplasmic reticulum by displacing ATP2A1/SERCA1 inhibitors, thereby acting as a key regulator of skeletal muscle activity (By similarity). Also enhances the activity of the ATP2A2/SERCA2 ATPase. Does not directly stimulate SERCA pump activity (By similarity). Binds preferentially to the phosphorylated E1 and E2 conformational forms of ATP2A2 which predominate at high Ca(2+) concentrations during the systolic phase of the cardiac cycle (By similarity). Competes with ATP2A2 inhibitor phospholamban (PLN) for binding to ATP2A2 and displaces PLN. Can activate ATP2A2 directly in the absence of PLN. Also enhances sarcoplasmic reticulum Ca(2+) uptake and myocyte contractility by displacing the SERCA inhibitory peptides sarcolipin (SLN) and myoregulin (MRLN) (By similarity).
Synonyms: DWORF
Tractability: Antibody: UniProt predicts a signal peptide or a membrane-spanning region.
Gene: Protein-coding gene on chromosome 3 (155,290,227 to 155,293,683, reverse strand). Ensembl gene ENSG00000240045.
Subcellular location: Sarcoplasmic reticulum membrane
Gene Ontology:
Molecular function: protein binding; enzyme activator activity
Biological process: positive regulation of calcium ion import into sarcoplasmic reticulum; regulation of ATPase-coupled calcium transmembrane transporter activity; regulation of slow-twitch skeletal muscle fiber contraction
Cellular component: sarcoplasmic reticulum membrane
Homologues: Orthologues: chimpanzee STRIT1 (100% identical), macaque STRIT1 (100% identical), mouse Strit1 (74% identical).
Diseases named in the same sentence as STRIT1 in open-access papers:
STRIT1 is named in the same sentence as 14 diseases in open-access papers, as found by Europe PMC text mining. Sharing a sentence is not in itself a finding about the gene and the disease.
STRIT1 shares sentences with these, for which no sentence is quoted: heart failure (6 papers); cardiomyopathy (4); dilated cardiomyopathy (2); Duchenne muscular dystrophy (2); cancer (1); cardiovascular disease (1); congestive heart failure (1); diabetic cardiomyopathy (1); heart diseases (1); muscular dystrophy (1); Myocardial fibrosis (1); myocardial infarct (1); neurotoxicity (1); tumor (1).